NF2 (NF2, moesin-ezrin-radixin like (MERLIN) tumor suppressor)
Diseases named in the same sentence as NF2 in open-access papers (continued):
Sharing a sentence is not in itself a finding about the gene and the disease.
schwannoma (continued). "However, NF2 loss in the Schwann cell lineage could also lead to schwannoma development, and although the likelihood is very low, it is still possible that schwannomagenesis may result from NF2 loss/downregulation as a result of Lats1/2 loss." (PMID 32960816, 2020). "Further study of Hippo signaling in the context of NF2 mutation revealed that genetic and pharmacological inhibition of Yap led to decreased tumor cell proliferation and survival in NF2 mutant cells and was able to reduce schwannoma tumor growth in mouse transplant models." (PMID 31450674, 2019). "Thus, we tested the hypothesis that NF2 loss is necessary for schwannoma formation in schwannomatosis patients with germline SMARCB1 mutations." (PMID 28824165, 2017). "We previously identified fimepinostat, a dual histone deacetylase (HDAC)/phosphoinositide-3 kinase (PI3K) inhibitor, as a promising drug candidate with pro-apoptotic effects on NF2-related schwannomas." (PMID 41898501, 2026). "Compared with old series, the newest ones experienced a relative decline of schwannomas incidence and, therefore, of NF-2 cases." (PMID 41515625, 2026). "Our findings establish a critical role for FAK in schwannoma development and provide rationale for evaluation of combination FAK plus MEK inhibition in future clinical trials for NF2-associated SWN." (PMID 41616055, 2026). "Remarkably, a recurrent somatic fusion gene has been identified in 10% of sporadic schwannomas and in schwannomas of patients with NF2-related SWN." (PMID 40794298, 2025). "Pediatric schwannomas are most frequently seen in patients with neurofibromatosis type 2 (NF2) and to a lesser extent in patients with schwannomatosis (SMARC-B1 and LZTR1)." (PMID 39847050, 2025). "The analysis of a schwannoma in this patient indicated somatic loss of the wild-type SMARCB1 allele, in combination with NF2 loss." (PMID 40794298, 2025). "A few studies on schwannoma and mesothelioma have shown that Merlin immunohistochemistry is correlated with NF2 molecular status." (PMID 40815185, 2025). "To pinpoint the specific components within NF2-EVs that enhance MDSC transformation and stimulate the proliferation of NF2-associated schwannoma cells, we utilized mass spectrometry screening on NF2-EVs." (PMID 41149489, 2025). "The basis of the four-hit/three-step model is that all three tumour suppressor genes known to be relevant to schwannoma development, namely NF2, LZTR1 and SMARCB1, are located on chromosome 22q." (PMID 40794298, 2025). "Intra-dermal schwannomas are common in NF2-related SWN but very rare in patients with non-NF2-related SWN and even considered to be completely absent in non-NF2-related SWN." (PMID 40794298, 2025). "Instead, tumour-specific PVs in the NF2 gene characterize the schwannomas of patients with non-NF2-related SWN." (PMID 40794298, 2025). "One study reported that methylation of three CpG sites in the NF2 promoter region was found in up to 60% of schwannomas and correlated with decreased mRNA expression." (PMID 40815185, 2025). "The schwannoma–neurofibroma hybrid is one of the more commonly described HPNST variants and is frequently associated with NF1- and NF2-related schwannomatosis, as well as other forms of schwannomatosis." (PMID 40218204, 2025). "This module was functionally enriched for multiple terms related to ECM and actin filaments, which is consistent with the relationship between NF2 and F-actin cytoskeletal defects in schwannoma." (PMID 40585242, 2025). "Schwannomas in patients with schwannomatosis frequently exhibit tumour-specific intragenic NF2 PVs that are different in anatomically distinct schwannomas of a given patient, indicative of their somatic origin." (PMID 40794298, 2025). "The mGFAP-Cre; Smarcb1flox/flox;Nf2flox/flox mice developed tumorlets consisting of Schwann cells in the dorsal root ganglia, reminiscent of the schwannoma tumorlets found in NF2 patients." (PMID 40794298, 2025).
schwannoma (continued). "Future studies using this platform hold promise to reveal new insights into SC biology, NF2-SWN, and the role of ECM associated proteins in schwannoma pathogenesis." (PMID 40585242, 2025). "Given that the cells that initiate schwannoma formation are NF2(−/−) cells of the SC lineage, we applied a differentiation protocol towards the neural crest (NC)-SC axis." (PMID 40746735, 2025). "In schwannomas of patients with schwannomatosis, somatic biallelic NF2 gene inactivation is very frequent." (PMID 40794298, 2025). "Whilst biallelic NF2 gene inactivation is an absolute requirement for schwannoma growth in addition to biallelic SMARCB1 mutation, complete NF2 gene inactivation is dispensable for MRT development." (PMID 40794298, 2025). "The presence of multiple intracranial tumors, let alone separate ipsilateral schwannomas, is an incredibly rare occurrence outside of NF2." (PMID 39917261, 2025). "Furthermore, while humans with heterozygous NF2 mutations develop schwannomas associated with the inherited disorder neurofibromatosis type 2, Nf2 hemizygous mice do not exhibit the same phenotype, making them an inaccurate model for studying human NF2 mutant phenotypes." (PMID 39921490, 2025). "More than 70% of patients with schwannomatoses develop single or multiple hybrid neurofibroma/schwannoma tumors, while over 25% of patients with NF2-related schwannomatosis exhibit at least one hybrid neurofibroma/schwannoma tumor." (PMID 40218204, 2025). "These tumors mostly develop sporadically, but it is known that neurofibromas and schwannomas are associated with neurofibromatosis type 1 (NF1) and neurofibromatosis 2 (NF2), respectively." (PMID 40255822, 2025). "Testing for NF2 is therefore imperative in young patients less than 30 years of age with schwannomas of any location." (PMID 39941762, 2025). "The role of aberrant methylation is critical to the pathogenesis of NF2, as it leads to the inactivation of the NF2 gene, thereby contributing to the development of schwannomas and other tumours in NF2 patients." (PMID 40843672, 2025). "These tumorlets are considered to be small schwannomas exhibiting biallelic NF2 inactivation and occur mainly in the spinal nerve roots." (PMID 40794298, 2025). "Schwannomas, while less common in NF-1 than NF-2, do sometimes occur in NF-1 patients, most commonly along the cranial, spinal, or peripheral nerves." (PMID 40416267, 2025). "Reasons to reintroduce bevacizumab were hearing loss (n = 2, 50%), vestibular complaints (n = 1, 25%), and tumor progression of other NF2-related schwannomas (n = 1, 25%)." (PMID 38672561, 2024). "We next established a schwannoma xenograft model involving subcutaneous injection of NF2-KO Schwann cells into NOD SCID gamma (NSG) mice." (PMID 38879607, 2024). "The key regulatory pathway thought to be involved in NF2-mutant sporadic schwannomas is the Hippo signaling pathway." (PMID 39796693, 2024). "To further investigate the expression of proteases in VS, we employed a murine Nf2−/− schwannoma cell line (MD-MSC) and implanted them into the sciatic nerve of nude mice to establish tumor allografts." (PMID 38887507, 2024). "Approximately 8-Mb away from NF2 and commonly involved in schwannoma tumorigenesis is the LZTR1 gene." (PMID 39796693, 2024). "To study these mechanisms in human schwannoma cells, we used the HEI-193 cell line, which encodes heterozygous loss of NF2 on chromosome 22q and a distal splice site mutation in the remaining NF2 allele." (PMID 38216587, 2024). "Our previous study in NF2 mouse schwannoma models showed that long-term inhibition of mTORC1 by rapamycin inhibited tumorigenesis without significant toxicity." (PMID 38372904, 2024). "We showed that tyrosine nitration supports schwannoma cell proliferation and regulates cell metabolism in the inheritable tumor disorder NF2-related Schwannomatosis (NF2-SWN)." (PMID 38945076, 2024).
schwannoma (continued). "A recent clinical study investigated the use of vascular endothelial growth factor receptor (VEGFR) peptide vaccine in seven patients with progressive NF2-derived schwannomas." (PMID 39618887, 2024). "Partial knockdown of ACSL3 via doxycycline-inducible shRNA constructs impairs proliferation of NF2-KO cells in cell culture and also significantly impairs the growth of NF2-KO schwannoma xenografts." (PMID 38879607, 2024). "The values from this sequencing study indicated that NF2-mutant schwannomas had reduced regulation of the Hippo signaling pathway, promoting cell proliferation and the pathogenesis of sporadic schwannomas." (PMID 39796693, 2024). "Other indications included symptoms related to other NF2-related schwannomas (35%) and target tumor size (6%)." (PMID 38672561, 2024). "Schwannomas in the inner ear in NF2-patients usually present as secondary growth from the IAC to the inner ear." (PMID 38992191, 2024). "Loss of merlin function causes NF2-SWN, characterized by formation of schwannomas and other solid tumors (meningiomas and ependymomas) in the nervous system." (PMID 38945076, 2024). "In this study, we explored the use of bevacizumab as a treatment for NF2-related schwannomatosis, a condition characterized by the development of schwannomas on both vestibulocochlear nerves." (PMID 38672561, 2024). "The subsequent somatic hits occur in the schwannoma: two hits lead to the loss of the region of chromosome 22 containing the SMARCB1 and NF2 alleles (step 2), and the final hit mutates the remaining NF2 allele (step 3)." (PMID 39170644, 2024). "Genetic studies show that the NF2 gene on chromosome 22 plays an essential role in sporadic and syndromic schwannoma development." (PMID 38800239, 2024). "Conditional biallelic knockout of Nf2 using P0-Cre transgenic mice leads to the development of Schwannomas, cataracts, and tumors in tissues with neural crest-derived components." (PMID 39415595, 2024). "Herein, we present an intriguing case involving an atypical presentation of a schwannoma—specifically, a schwannoma in the gallbladder in a pediatric patient—which resulted in the incidental discovery of NF2 disease." (PMID 39618887, 2024). "HEI-193 cells have been a popular model for NF2-related schwannoma and were therefore included in many parts of this study." (PMID 39083549, 2024). "Bevacizumab has been tested as a vaccine injected subcutaneously to treat schwannomas in NF2 patients, demonstrating safety but only limited effects on schwannoma growth." (PMID 36549282, 2023). "The unique availability of a mouse model in which multiple Nf2-mutant schwannomas develop synchronously in anatomically defined locations provides an opportunity to quantitatively and deeply study schwannoma heterogeneity." (PMID 36944680, 2023). "Consistently, conditional knockout mice with Cre-mediated excision of NF2 in schwann cells developed schwannomas, schwann cell hyperplasia, cataract, and osseous metaplasia." (PMID 36937440, 2023). "Targeted deletion of the Nf2 gene in mouse Schwann cells leads to schwannoma and Nf2-null cells have impaired contact inhibition of growth in vitro." (PMID 36809290, 2023). "Inactivation of the tumor suppressor gene NF2 plays a major role in the genesis of conventional schwannomas." (PMID 37813009, 2023). "Schwannomas located at the CCJ are rare, with the clinical presentation variable and sometimes in association with NF2." (PMID 36479403, 2022). "Biallelic inactivation of NF2 represents the primary or sole oncogenic driver event in the vast majority of schwannomas." (PMID 35986430, 2022). "Indirect evidence of the association between VEGF and schwannoma growth is provided by the effect of bevacizumab, an anti-VEGF antibody used to treat patients with NF2." (PMID 36672540, 2022).
schwannoma (continued). "We conducted an unbiased chemical compound screen of the Library of Pharmacologically Active Compounds (LOPAC) as a pilot high-throughput screen to identify NF2 schwannoma targets for inhibition." (PMID 35875610, 2022). "The researchers then deleted the neurofibromatosis 2 suppressor gene (NF2) in schwannoma cells and, as expected, noted increased intraganglionic schwannoma cell proliferation." (PMID 36230740, 2022). "The new classification of schwannomatoses is based on the coupling of the causative genes (i.e., NF2, SMARCB1 and LZTR1) and on the histological hallmark of these syndromes (i.e., schwannomas)." (PMID 35741273, 2022). "CUDC907 has cytotoxic activity in NF2 schwannoma models and primary VS cells and is a candidate for clinical trials." (PMID 35875610, 2022). "Neurosurgical removal remains the first line of therapy, yet NF2 schwannomas present a higher recurrence rate than in individuals without the disease." (PMID 35053664, 2022). "Despite their precocity and high prevalence, dermatological lesions, that is, cutaneous tumours, led to the NF2 diagnosis in only four cases after excision and discovery of a schwannoma (n = 3) or neurofibroma (n = 1)." (PMID 35729665, 2022). "This was followed by focal neurological deficits (29%) and growth progression (23%) in NF2-associated schwannomas and by growth progression (21%) and focal neurological deficits (15%) in SWNT-associated schwannomas." (PMID 35771312, 2022). "Four of these children underwent resection with cytopathological examination leading to the diagnosis of schwannoma (n = 3) or neurofibroma (n = 1) and subsequently NF2 diagnosis at 1, 6, 8 and 13 yo respectively." (PMID 35729665, 2022). "Despite the significant phenotypical overlap between SWN and NF2, especially considering that schwannomas are the predominant tumors in both diseases; SWN is conventionally regarded as the third form of neurofibromatosis." (PMID 35053664, 2022). "In the past, NF2- PNP was thought to occur as a consequence of a compressive mass effect of schwannomas to adjacent peripheral nerves." (PMID 35453828, 2022). "Schwannomas are composed almost entirely of neoplastic Schwann cells and occur in patients with NF2 and schwannomatosis." (PMID 33669386, 2021). "Radiotherapy in schwannomas is also well described regarding vestibular schwannomas in cases of NF2." (PMID 33804067, 2021). "Lapatinib was identified for potential use for NF2-associated vestibular schwannomas due to increased expression of both EGFR and Erb2 in tumor tissue and inhibited proliferation in schwannoma cell lines." (PMID 34885143, 2021). "Schwannomatosis is clinically similar to NF2, but patients tend to develop schwannomas that spare the vestibular nerve." (PMID 33669386, 2021). "Recently, a clinical trial using VEGFR1/2 peptide vaccine was also conducted in patients with progressive NF2-derived schwannomas, showing hearing improvement and tumor volume reduction." (PMID 34072574, 2021). "When possible, sporadic and NF-2 related VS should be distinguished from schwannomatosis, which is a distinct clinical and molecular entity which results in schwannomas throughout the body." (PMID 33445724, 2021). "These Schwannomas occur in the tongue more frequently than other regions in the oral cavity, suggesting a region‐specific role of Nf2 in oral tumourigenesis." (PMID 34697858, 2021). "2:33 Schwannomas in NF2 are often polyclonal, making functional and anatomical preservation of the cochlear nerve unfeasible." (PMID 36285231, 2021). "Associated schwannomas show a combination of “first and second hits” of SMARCB1, LZTR1, NF2 and others." (PMID 33863389, 2021). "Patients with NF2 can suffer from multiple central or peripheral nervous system tumors, including schwannomas, meningiomas, and ependymomas." (PMID 33572546, 2021).
schwannoma (continued). "Although biallelic mutations of SMARCB1 or LZTR1 have been detected in the patients with SWN, the classical two-hit model of tumorigenesis is insufficient to account for schwannoma growth, since NF2 is frequently inactivated in these tumors." (PMID 34072574, 2021). "The underlying cause for the predilection of formation of NF2-associated schwannomas along the branches of the vestibular nerve relative to other cranial nerves remains uncertain, and investigation of this question may provide interesting insights into the biology of NF2 and schwannomas." (PMID 31161239, 2020). "In NF2, schwannomas can develop along peripheral, spinal, and cranial nerves, and they often develop along the eighth cranial nerve, resulting in bilateral acoustic (vestibular) schwannomas that cause hearing and balance problems." (PMID 32960816, 2020). "Particularly, ATM, accounting for 33% of the samples, was the most frequently mutated cancer-related gene in schwannoma, followed by CHD4, FAT1, KMT2D, MED12, NF2, and SUFU (>20%)." (PMID 33193598, 2020). "Plexiform lesions in patients with NF2 are typically revealed to represent plexiform schwannomas, in contrast to the plexiform neurofibromas of NF1." (PMID 31161239, 2020). "Loss of SMARCB1 was also related to Schwannoma, another phenotype found in NF1 despite being more frequent in NF2." (PMID 32858845, 2020). "Research on Neurofibromatosis type 2 (NF2) and schwannoma pathobiology in recent years has moved toward a better mechanistic understanding of the interplay and crosstalk between the different cell types within the tumor." (PMID 32616891, 2020). "Inhibition of cMET reduced tumor growth and sensitized schwannomas to radiation in mouse models, providing one potential avenue to reduce radiotoxicity in NF2 patients." (PMID 31161239, 2020). "The fact that this oxidant exerts a tight, selective regulation on the metabolic shift in human NF2 schwannoma cells provides promising molecular targets for drug development among the proteins oxidized by peroxynitrite." (PMID 31171721, 2019). "Frequent loss of the second allele in combination with biallelic loss of NF2 has been reported in such tumor tissues, indicating that SMARCB1 acts as a tumor suppressor in schwannomas and that the familial SMARCB1 mutations lead to a loss-of-function." (PMID 31273213, 2019). "Oxidized proteins constitute a novel target for therapeutic development not only for the treatment of NF2 schwannomas but also other tumors in which peroxynitrite plays a regulatory role." (PMID 31171721, 2019). "Together these observations reveal that peroxynitrite plays an important role in the regulation of the metabolic phenotype of NF2 schwannoma cells." (PMID 31171721, 2019). "Differences in VEGF/VEGFR status and key molecules and cells in the tumor microenvironment between NF2 and non-NF2 schwannomas, and between NF2 schwannomas pre-vaccination and post vaccination, are also analyzed." (PMID 31848332, 2019). "A review of the literature suggests that schwannoma shrinkage and hearing improvement occur in >50% of progressive NF2 patients treated with bevacizumab 6,13–20." (PMID 31848332, 2019). "FUS/TLS (fused in sarcoma or translocated in liposarcoma) was identified as a translocated gene in human liposarcoma and leukemia and NF2 in human neurofibrosarcoma and schwannoma." (PMID 31105870, 2019). "In NF2, they usually appear bilaterally, and compared to sporadic schwannomas, they grow faster and are much more adherent to the cranial nerves and the brainstem." (PMID 31245296, 2019). "More importantly, VEGFR1 and VEGFR2 were expressed on tumor cells in schwannomas in NF2 patients, suggesting that NF2 schwannomas themselves can be direct targets of VEGFRs vaccination." (PMID 31848332, 2019).